SNORD3G (small nucleolar RNA, C/D box 3G)
Gene: Small nucleolar RNA gene on chromosome 1 (90,657,750 to 90,657,964, forward strand). Ensembl gene ENSG00000199666.
Gene Ontology:
Biological process: RNA processing
Cellular component: nucleolus
Homologues: Orthologues: chimpanzee U3 (99% identical), macaque U3 (87% identical), rabbit U3 (66% identical). Paralogues in human: U3 (84% identical), U3 (83% identical), SNORD3P1 (82% identical), U3 (82% identical), SNORD3E (81% identical), U3 (81% identical), U3 (80% identical), SNORD3D (80% identical), SNORD3H (79% identical), U3 (79% identical), U3 (78% identical), U3 (77% identical), and 12 more.